INSL4 (insulin like 4)
Description:
May play an important role in trophoblast development and in the regulation of bone formation.
Synonyms: EPIL; PLACENTIN
Tractability: Antibody: UniProt places it where antibodies can reach, with medium confidence; UniProt predicts a signal peptide or a membrane-spanning region; its Gene Ontology location is reachable by antibodies, with medium confidence. PROTAC: ubiquitination databases record sites on it.
Gene: Protein-coding gene on chromosome 9 (5,231,419 to 5,235,304, forward strand). Ensembl gene ENSG00000120211.
Subcellular location: Secreted
Subcellular location (Human Protein Atlas): Vesicles; Predicted to be secreted
Gene Ontology:
Molecular function: insulin-like growth factor receptor binding; signaling receptor binding; hormone activity
Biological process: cell-cell signaling; positive regulation of chorionic trophoblast cell proliferation; signal transduction
Cellular component: extracellular region
Genetic constraint (gnomAD): Loss-of-function variants: 7 observed, 6.36 expected, observed/expected ratio (o/e) 1.1, 90% interval 0.62 to 1.82. That is too few expected variants to judge how well the gene tolerates losing a copy. Missense variants: 217 observed, 165.17 expected, observed/expected ratio (o/e) 1.31, 90% interval 1.17 to 1.47. Synonymous variants: 76 observed, 66.41 expected, observed/expected ratio (o/e) 1.14, 90% interval 0.95 to 1.38.
Homologues: Orthologues: chimpanzee INSL4 (98% identical), macaque INSL4 (91% identical), dog RLN2 (27% identical). Paralogues in human: RLN1 (32% identical), RLN2 (32% identical), INSL6 (15% identical).
Diseases named in the same sentence as INSL4 in open-access papers:
INSL4 is named in the same sentence as 14 diseases in open-access papers, as found by Europe PMC text mining. Sharing a sentence is not in itself a finding about the gene and the disease. The quoted sentences say what the papers report.
breast carcinoma (4 papers, 2005 to 2021). "High expression of INSL4 can promote breast cancer invasion and motility by influencing lateral Her2 signaling in vitro cell experiments." (PMID 34612148, 2021). "Although INSL4 is produced by invasive breast cancer cells and is co-expressed with HER-2 in a cluster of cells in the invasive front of neoplasia 11, 12, little is known about involvement of INSL4 in NSCLC." (PMID 34093787, 2021). "INSL4 upregulation was previously identified in a breast cancer cell subclone with increased invasiveness through in vitro selection." (PMID 33102522, 2020). "Insulin-like growth factor 4 (INSL4), also down-regulated in 12.2, has been reported to be over-expressed in highly invasive breast cancer cells." (PMID 16083501, 2005).
lung carcinoma (4 papers, 2021 to 2022). "Aberrant INSL4 signaling drove the growth and survival of LKB1-deficient lung cancer cells." (PMID 34612148, 2021). "Aberrant INSL4 signaling is related to LKB1-inactivated lung cancer." (PMID 34503106, 2021). "Insulin-like 4 (INSL4) has been reported to be required for the growth and viability of LKB1-inactivated lung cancer." (PMID 36294477, 2022). "These individual CRTC knockout cells showed a reduction in expression of several CREB-mediated target genes, such as PDE4D, INSL4, LINC00473, and NR4A2, but not to the extent of their endogenous levels in LKB1-wt lung cancer H522 cells, as assayed by western blotting or RT-qPCR assays." (PMID 34142658, 2021).
non-small cell lung carcinoma (4 papers, 2020 to 2022). A group of at least three distinct histological types of lung cancer, including non-small cell squamous cell carcinoma, adenocarcinoma, and large cell carcinoma. "INSL4 signaling is a potential vital for LKB1-inactivated non-small-cell lung carcinoma, and its introduction helps to develop novel and effective anti-tumor strategies." (PMID 33102522, 2020). "A recent study showed that INSL4 might be a prognostic marker for proliferation and invasiveness in non-small cell lung cancer (NSCLC)." (PMID 36294477, 2022). "INSL4 as prognostic marker for proliferation and invasiveness in Non-Small-Cell Lung Cancer." (PMID 36313444, 2022).
lung adenocarcinoma (1 paper, 2022). A carcinoma that arises from the lung and is characterized by the presence of malignant glandular epithelial cells. "Finally, seven copper death genes related to lung adenocarcinoma were screened out, including ARHGEF39, EFCC1, SERPIND1, INSL4, ANLN, RHOV and CCL20." (PMID 36313444, 2022).
prostate carcinoma (1 paper, 2022). A carcinoma that arises from epithelial cells of the prostate gland. "Our results suggested that determined common hsa-miR-494-3p, hsa-miR-3128, hsa-miR-8084 and their target HIF1A, AVRP1A, NHS, INSL4 may play a crucial role in therapeutic and early diagnostic strategies for prostate cancer." (PMID 36326314, 2022). "Decreased levels of hsa-miR-494-3p, hsa-miR-3128, hsa-miR-8084 and therefore likely to increase levels of targets HIF1A, AVRP1A, NHS, INSL4 may be novel biomarker candidates for early-stage diagnosis and treatment of prostate cancer." (PMID 36326314, 2022). "Also, it is mentioned in many studies that the predicted targets HIF1A, AVRP1A, NHS, INSL4 have a very important role in the progression of prostate cancer." (PMID 36326314, 2022).
cancer (4 papers, 2021 to 2023). A tumor composed of atypical neoplastic, often pleomorphic cells that invade other tissues. "In non-hematopoietic cancer cells, INSL4 expression can result in an autocrine loop, and INSL4 has been proposed as a cancer prognostic marker." (PMID 37284191, 2023). "To substantiate a clinically relevant tumourigenic role for INSL4, we used cancer outlier profile analysis as applied to the web-accessible GENT2 microarray database, containing samples from the Affymetrix U133Plus 2.0 platform." (PMID 34093787, 2021). "Cancer outlier profile analysis using the web-accessible database confirmed the tumour-promoting function of INSL4 as related to clinical outcome in NSCLC." (PMID 34093787, 2021). "INSL4 expression assessed in a set of different cancer histotypes revealed remarkable INSL4 expression mostly occurring in LC tissues relative to control counterparts." (PMID 34093787, 2021). "INSL4 was first discovered in the placenta tissue and belongs in the relaxin/insulin-like family of peptides, which have been credited over the years with a functional role in cancer 12, 18, 21, 32-34." (PMID 34093787, 2021). "The RNAs with significantly higher expression levels in cancer tissues than in normal tissues include PELATON, INSL4, PSG1, PSG4." (PMID 35454778, 2022). "In our previous studies, we also showed that LKB1-deficiency led to CRTC activation of many CREB-dependent genes, including NR4A2, PTGS2 (aka COX-2), LYPD3, INSL4, and LINC00473, which play important roles in cancer cell growth, survival or invasive properties." (PMID 34142658, 2021). "We explored INSL4 function in NSCLC adenocarcinoma cells by using a Gain-of-Function approach, which is an excellent/benchmark tool for assessing the functional importance of cancer-related genes." (PMID 34093787, 2021).
tumor (4 papers, 2020 to 2022). "Here we demonstrate that INSL4 is an active tumour-promoting gene in NSCLC, in that it favours proliferation, invasion and migration of LC cells." (PMID 34093787, 2021). "On enumerating mitotic cells in both types of tumour, a 2.7-fold increase was found in INSL4-overexpressing masses." (PMID 34093787, 2021). "We investigated the signalling pathways engaged in INSL4 overexpressing cells and the tumour growth ability by studying the tumour development in a patient derived tumour xenograft mouse model." (PMID 34093787, 2021). "Because INSL4 has a functional in vitro effect in NSCLC proliferation and invasion, we investigated any contributions of INSL4 to tumour growth in vivo." (PMID 34093787, 2021). "Likewise, in the in vitro setting, we detected MAPK and AKT activation in extracts from INSL4-overexpressing tumour masses." (PMID 34093787, 2021). "The mRNA level of CR2, INSL4, FGF5, RAET1L and TNFRSF13B was upregulated in LUAD tumor tissues compared with paired normal tissues whereas AGER was downregulated." (PMID 36294477, 2022). "Nevertheless, because INSL4 is not expressed in normal lung, we observed that overexpression of INSL4 significantly correlated with poor overall survival and post tumour progression survival in a large public clinical microarray database of 4,142 LC patients." (PMID 34093787, 2021).
adenocarcinoma (1 paper, 2021). A common cancer characterized by the presence of malignant glandular cells. "By combining the results obtained from the in vitro and in vivo models and patients our results provide evidence for a potentially important role for INSL4 in the biology of adenocarcinoma NSCLC." (PMID 34093787, 2021). "In an in vitro setting, NSCLC adenocarcinoma H1299 cell line was used as a mean of identifying signalling pathways, which - upon activation by INSL4 overexpression - might affect cell growth and drug responsiveness." (PMID 34093787, 2021). "Moreover, in silico analysis for assessing patients whose NSCLCs adenocarcinoma spontaneously expressed high levels of INSL4, a significant inverse correlation was found to occur between levels of INSL4 expression with poor Overall Survival (OS)." (PMID 34093787, 2021). "Thus, we analysed expressed levels of INSL4 in patients with NSCLCs adenocarcinoma." (PMID 34093787, 2021).
INSL4 also shares sentences with these, for which no sentence is quoted: diabetes (1 paper); leukemia (1); lymphoma (1); preeclampsia (1); squamous cell carcinoma (1); ZIKV infection (1).